MALAT1 (metastasis associated lung adenocarcinoma transcript 1)
Diseases named in the same sentence as MALAT1 in open-access papers (continued):
Sharing a sentence is not in itself a finding about the gene and the disease.
Sepsis (continued). "In sepsis patients, lncRNA metastasis-associated lung adenocarcinoma transcript 1 (lnc-MALAT1) and miR-125a are positively correlated with APACHE-II and SOFA scores, making the lnc-MALAT1/miR-125a axis a predictor of increased 28-day mortality risk." (PMID 39201697, 2024). "Malat1 is a lncRNA whose participation in sepsis pathophysiology has been well investigated." (PMID 38385073, 2024). "Our findings showed that MALAT1 is aberrantly upregulated in sepsis‐induced AKI models." (PMID 39390627, 2024). "MALAT1-knockout mice exhibited reduced inflammation and death upon sepsis induction." (PMID 37509544, 2023). "Thus, macrophage MALAT1 levels increase during LPS-induced macrophage activation and sepsis development." (PMID 37509544, 2023). "LncRNA MALAT1 could accelerate inflammatory response by promoting neutrophil migration, and finally aggravating the progression of sepsis." (PMID 36817490, 2023). "It has been reported that MALAT1 is highly expressed in septic patients or mice with sepsis model." (PMID 37398640, 2023). "For example, long non-coding metastasis-associated lung adenocarcinoma transcript 1 (lnc-MALAT1) and micro RNA (miR)-125a were increased in sepsis patients compared with healthy controls and positively correlated with APACHE-II score, SOFA score, serum creatinine, CRP, TNF-α, IL-1β, IL-6, and IL-8." (PMID 34991675, 2022). "In addition, MALAT1 regulates the p38 MAPK/NF-κB signaling pathway by interacting with miR-125b, causing worsening of sepsis, heart inflammation, and dysfunction." (PMID 35635083, 2022). "Furthermore, long chain genes lncRNA NEAT1 and Lnc-MALAT1 can modulate the progression of sepsis through sponging miR-370-3p [35, -37]." (PMID 35722711, 2022). "Consistently, we observed MALAT1 upregulation in patients with sepsis." (PMID 35300579, 2022). "further demonstrated that MALAT1 could protect the lung from sepsis-induced injury via inhibiting NF-κB signaling." (PMID 34630395, 2021). "Importantly, literature reveals that lncRNA MALAT1 can relieve the symptoms of sepsis-induced acute lung injury via TLR4/NF-κB and p38 MAPK signaling pathways." (PMID 34516310, 2021). "Recently, it has been reported that lncRNA MALAT1 is an ideal marker for the diagnosis of sepsis." (PMID 34240756, 2021). "Previous studies have suggested that lncRNAs may be potential biomarkers for prognosis of sepsis, such as lncRNAs MALAT1, NEAT1, RP11-1220 K2.2.1–7, ANXA3–2, TRAPPC5–1, and ZNF638–1, which have been introduced in introduction." (PMID 34483898, 2021). "Moreover, a prospective cohort study confirmed the high predictive value for MALAT1 in differentiating patients with sepsis, indicating the potential of MALAT1 to be developed a biomarker to facilitating management in septic patients." (PMID 34630395, 2021). "Furthermore, the expression of MALAT1 was elevated during sepsis, and thus inhibited cell proliferation and apoptosis in LPS-induced acute kidney injury." (PMID 34630395, 2021). "However, the role of lncRNA MALAT1 in the pathology and physiology of sepsis still needed to be further explored." (PMID 34240756, 2021). "In sepsis, genes or gene modules inducted by MALAT1 may modulate their expression pattern in endothelial cells, which is critical as MALAT1 has been reported to mediate inflammation in traumatic brain injury." (PMID 32471511, 2020). "In addition, we analyzed the association of lnc‐MALAT1/miR‐125a axis with survival profiles in sepsis patients and observed that lnc‐MALAT1/miR‐125a axis was of value in predicting 28‐day mortality risk." (PMID 32309886, 2020). "MALAT1 plays a regulatory role in the inflammatory process of sepsis." (PMID 33204219, 2020). "In sepsis patients, lnc‐MALAT1/miR‐125a axis was decreased in survivors (7.048 [3.112‐20.334]) compared with deaths (14.408 [6.287‐38.709]) (P < .001), and lnc‐MALAT1 relative expression was also reduced in survivors (2.266 [1.311‐3.738]) compared with deaths (3.026 [1.901‐6.032]) (P < .001)." (PMID 32309886, 2020).
Sepsis (continued). "We found that lnc‐MALAT1/miR‐125a axis was positively associated with APACHE II score, SOFA score, Scr, CRP, TNF‐α, IL‐1β, IL‐6, and IL‐8, while negatively associated with albumin in sepsis patients." (PMID 32309886, 2020). "However, further studies are still required to investigate the value of lncRNA MALAT1 in sepsis based on human skeletal muscle tissues to further validate its potential as a novel therapeutic target for sepsis treatment." (PMID 31830649, 2020). "Furthermore, lnc‐MALAT1/miR‐125a axis presented numerically higher value of AUC compared with lnc‐MALAT1 and miR‐125a, suggesting the increased value of lnc‐MALAT1/miR‐125a axis in distinguishing sepsis patients from healthy controls." (PMID 32309886, 2020). "(c) High lnc‐MALAT1/miR‐125a axis predicted increased 28‐day mortality in sepsis patients." (PMID 32309886, 2020). "Moreover, lncRNA MALAT1 expression was negatively correlated with miR‐125b level in both sepsis patients (P < 0.001) and HCs (P < 0.001)." (PMID 31301104, 2019). "LncRNA MALAT1 could be developed as a potential biomarker for facilitating diagnosis and management in sepsis patients." (PMID 31301104, 2019). "In conclusion, lncRNA MALAT1 could be developed as a biomarker for facilitating diagnosis and management in sepsis patients." (PMID 31301104, 2019). "It remains to be determined how, if at all, upregulation of MALAT-1 impinges on LPS induced sepsis." (PMID 31231228, 2019). "Moreover, we evaluated the correlation between lncRNA MALAT1 expression and miR‐125b expression in plasma, and found that lncRNA MALAT1 expression was negatively correlated with the miR‐125b expression in both sepsis patients (P < 0.001) and HCs (P < 0.001)." (PMID 31301104, 2019). "MALAT1 has been implicated in the positive regulation of inflammatory processes induced by hyperglycemia, but its participation in sepsis has not been documented before." (PMID 29657277, 2017). "Therefore, we further explored whether MALAT1 affected ferroptosis during sepsis‐induced AKI through regulation of ACSF2." (PMID 39390627, 2024). "Thus, silencing MALAT1 by miR-26a-5p from MSC-derived exosome ameliorates liver injury in sepsis." (PMID 37398640, 2023). "Thus, the findings of the present study suggest that MSCs, MSC-derived exosome and miR-26a-5p are potential therapeutics, and MALAT1 is a promising target for the treatment of ALI in sepsis, which provides a new avenue and new insights for rescuing the syndrome." (PMID 37398640, 2023). "In addition to AP, MALAT1 expression was elevated in the plasma of sepsis and ARDS patients." (PMID 36354526, 2022). "Therefore, we hypothesized that MALAT1 might interact with CRNDE to participate in LPS pathways involved in sepsis." (PMID 35300579, 2022). "Furthermore, several studies suggested that lncRNA MALAT1 could also participate in the process of sepsis and may be a potential biomarker for sepsis." (PMID 34055659, 2021). "Lnc‐MALAT1 was positively correlated with Scr (r = .254, P < .001), CRP (r = .494, P < .001), TNF‐α (r = .387, P < .001), IL‐1β (r = .330, P < .001), IL‐6 (r = .431, P < .001), and IL‐8 (r = .420, P < .001), while negatively associated with albumin (r = −.153, P = .033) in sepsis patients." (PMID 32309886, 2020). "Furthermore, we found that CRNDE and MALAT1 may act as miRNA sponges of sepsis related miRNAs to regulate the expression of sepsis modules." (PMID 32471511, 2020). "Hence, the current study was designed with the aim of investigating the potential role of lncRNA MALAT1 in the initiation and development of sepsis, and we have demonstrated that lncRNA MALAT1 functions through the EZH2/BRCA1/AKT-1 axis to affect the progression of sepsis." (PMID 31830649, 2020). "Higher MALAT1 (p < 0.01) and lower CRNDE (p < 0.01) levels were identified in sepsis samples than in control samples." (PMID 35300579, 2022). "Therefore, besides CRNDE, other factors may also regulate MALAT1 expression in sepsis." (PMID 35300579, 2022).
Sepsis (continued). "It was observed that MALAT1 and CRNDE were inversely and significantly correlated with each other across both sepsis and control plasma samples." (PMID 35300579, 2022). "Correlations between MALAT1 and CRNDE across plasma samples from both sepsis patients and healthy controls were analyzed using linear regression." (PMID 35300579, 2022). "We first examined changes in MALAT1 and CRNDE levels in plasma samples from both sepsis patients (n = 60) and healthy controls (n = 60) using RT-qPCR." (PMID 35300579, 2022). "It has been reported that long non-coding RNAs (lncRNAs) metastasis-related lung adenocarcinoma transcript 1 (MALAT1) and colorectal neoplasia differentially expressed (CRNDE) play opposite roles in sepsis." (PMID 35300579, 2022). "They identified five sepsis-related lncRNAs, including FENDRR, MALAT1, TUG1, CRNDE, and ANCR, whose functions were highly related with biological processes of sepsis." (PMID 34055659, 2021). "At present, studies of lncRNA expression in sepsis mainly focus on HOTAIR, MALAT1, NEAT1, TUG1, and UCA1." (PMID 34514170, 2021). "NEAT1, MALAT1, THRIL, XIST, MIAT and TUG1 are among lncRNAs that participate in the pathoetiology of sepsis-related complications." (PMID 34956235, 2021). "Similar to MALAT1, NEAT1 can promote the progression of sepsis through promoting cell apoptosis, enhancing immune response, and decreasing cellular activity." (PMID 34630395, 2021). "MALAT1 also interacts with p38 MAPK/NF-kB and miR-125b to aggravate cardiac inflammation and dysfunction in sepsis." (PMID 34041287, 2021). "It was indicated that lncRNA MALAT1 was significantly upregulated and BRCA1 was significantly downregulated in the sepsis group." (PMID 31830649, 2020). "Both MALAT1 and CRNDE regulate ten sepsis modules and they share seven common modules, six out of them are down-regulated." (PMID 32471511, 2020). "Flow cytometry was used to detect apoptosis of skeletal muscle cells of sepsis, which revealed that sh-MALAT1 + oe-EZH2 + sh-AKT-1 significantly inhibited cell apoptosis as compared with sh-MALAT1 + oe-EZH2." (PMID 31830649, 2020). "However, the expression of lncRNA MALAT1 and its significance in sepsis remain largely unknown." (PMID 31830649, 2020). "We identified five sepsis lncRNAs, FENDRR, MALAT1, TUG1, CRNDE, and ANCR, all of which connect five or more sepsis modules, indicating their functions are highly related with biological processes of sepsis." (PMID 32471511, 2020). "lncRNA MALAT1 was noted to regulate the expression and export from the nucleus of BRCA1 by recruiting zeste homolog 2 (EZH2) in skeletal muscle cells of sepsis." (PMID 31830649, 2020). "To further explore the potential relationship between lncRNA MALAT1 and BRCA1, we induced a sepsis model using human skeletal muscle cells (HSMKMC 3500) by LPS treatment." (PMID 31830649, 2020). "MALAT1 can regulate the p38 MAPK/NF‐κB pathway by regulating miR‐125b, which aggravates cardiac inflammation and dysfunction induced by sepsis." (PMID 33047847, 2020). "Five lncRNAs, FENDRR, MALAT1, TUG1, CRNDE, and ANCR, were detected as sepsis regulators based on the interactions among lncRNAs and the identified coexpression modules." (PMID 32471511, 2020). "The results from the current study show that along with lnc-IL17R, lncRNAs MALAT-1, HULC, and UCA1 are also upregulated during LPS induced sepsis." (PMID 31231228, 2019). "MALAT1 expression is increased in LPS-activated macrophages, cardiac microvascular endothelial cells (CMVEC), and in the hearts of rats with sepsis." (PMID 29662883, 2018). "Recent investigations have revealed artesunate’s capacity to modulate various molecular pathways, including the MALAT1/PTBP1/IFIH1 axis in sepsis, long non-coding RNA RP-11 in hepatic epithelial-mesenchymal transition (EMT), and the MALAT1/YAP signaling pathway in C918 cells." (PMID 40758729, 2025).
Sepsis (continued). "To further confirm the pattern of Malat1 expression in sepsis-induced PMN-MDSCs, we performed the induction of MDSCs from BMCs in vitro and investigated the activation and function of MDSCs, as well as the expression of Malat1." (PMID 38385073, 2024). "Our single-cell sequencing data demonstrated that sepsis marker genes were highly elevated in CD16+ monocytes, including NAP1L1, CFD, BID, BCL2A1, MALAT1, RNH1, and LILRA5 genes." (PMID 39294473, 2024). "Therefore, large-scale studies will be needed to confirm the detailed mechanisms of MALAT1, miR-26a-5p, MSCs-derived exosome, and MSCs pathway in ALI injury of sepsis through animal experiments and clinical tests in the future." (PMID 37398640, 2023). "In conclusion, MSCs, MSCs-derived exosome and miR-26a-5p could effectively protect against sepsis-induced ALI by inhibiting MALAT1 and MALAT1-enhanced oxidative stress." (PMID 37398640, 2023). "Therefore, this study was carried out to analyze the roles of MALAT1 and CRNDE in sepsis and to explore their potential interactions." (PMID 35300579, 2022). "Recently, emerging studies have revealed that some lncRNAs, such as NEAT1, MALAT1, and ANRIL, could participate in the progression of sepsis and serve as a potential biomarker for sepsis." (PMID 35910890, 2022). "We found that MALAT1 was upregulated and CRNDE was downregulated in sepsis." (PMID 35300579, 2022). "MALAT1 is upregulated in sepsis and CRNDE is downregulated in sepsis." (PMID 35300579, 2022). "After proper treatment, MALAT1 was downregulated and CRNDE was upregulated in sepsis." (PMID 35300579, 2022). "The lncRNA MALAT1 can alleviate sepsis in burn-injured patients by regulating miR-214/TLR5; the lncRNA CRNDE is involved in aggravating the inflammatory process of sepsis through the miR-181a-5p/TLR4 axis." (PMID 36274974, 2022). "This study explored the interaction between MALAT1 and CRNDE in sepsis." (PMID 35300579, 2022). "While MALAT1 and NEAT1 promoted sepsis-induced inflammation in organ injury, TUG1 exhibited protective effects by inhibiting apoptosis, promoting cell proliferation, and downregulating immune response in sepsis." (PMID 34630395, 2021). "A study on 152 patients with sepsis found increased lncRNA MALAT1 expression in patients with ARDS compared to those without ARDS." (PMID 34055659, 2021). "While the research that exploring the mechanisms of MALAT1 in sepsis-related renal dysfunction was lacking, CASC2 was observed to inhibit inflammation mediated by NF-κB signaling pathway in human renal tubular epithelial cells." (PMID 34630395, 2021). "Only MALAT1 and TUG1 were detected (RPKM > 0.2 in at least two samples of one group) in the RNA-seq data, and their expression levels were significantly different between no_sepsis and sepsis samples." (PMID 34483898, 2021). "A prediction from the lncATLAS website and a RNA-FISH assay in the present study revealed that both lncRNA MALAT1 and EZH2 were located in the nucleus, indicating that lncRNA MALAT1 and EZH2 might interact with each other in skeletal muscle cells in sepsis." (PMID 31830649, 2020). "Collectively, the expressions of lncRNA MALAT1, BRCA1, and EZH2 were analyzed, with the predictive results obtained indicating that lncRNA MALAT1, BRCA1, and EZH2 are involved in the progression of sepsis." (PMID 31830649, 2020). "In addition, downregulation of lncRNA MALAT1 and EZH2 induced by ulinastatin confers a protective effect against LPS-induced CMVEC hyperpermeability and apoptosis in sepsis." (PMID 31830649, 2020). "Five sepsis lncRNAs were ultimately identified, FENDRR, MALAT1, TUG1, CRNDE, and ANCR." (PMID 32471511, 2020). "Second, the molecular mechanisms of lncRNA MALAT1 in promoting the development or progression of sepsis was not evaluated in our study." (PMID 31301104, 2019).
Sepsis (continued). "Our data showed that STAT3 was significantly activated from CLP day 1, while Malat1 expression changed with the progression of sepsis, suggesting that Malat1 may not directly affect STAT3 activation." (PMID 38385073, 2024). "Overall, MALAT1 might form a negative feedback loop with CRNDE in sepsis to regulate lung cell apoptosis." (PMID 35300579, 2022). "Moreover, it was found that elevation of proinflammatory cytokines caused by burn injury or post–burn infection was attenuated by treatment with lncRNA MALAT1 via the miR-214/TLR5 axis, thus providing a better understanding of the pathological regulation of post-burn sepsis." (PMID 34055659, 2021). "Previous study reported that MALAT1 bound to miR-23a to upregulate the expression of mast cell-expressed membrane protein (MCEMP) 1, hence promoting the inflammatory response in sepsis, indicating that lncRNAs could affect the development of sepsis through diverse signaling pathways." (PMID 34630395, 2021). "Therefore, lncRNA MALAT1 could potentially regulate the expression and export from the nucleus of BRCA1 in sepsis." (PMID 31830649, 2020). "We have not investigated the effect that by altering Malat1 expression in vivo may have on sepsis." (PMID 38385073, 2024). "Therefore, MALAT1 and CRNDE may participate in sepsis in a LPS-dependent manner." (PMID 35300579, 2022). "Therefore, altered expression of MALAT1 and CRNDE may participate in sepsis." (PMID 35300579, 2022). "However, the role of lnc‐MALAT1/miR‐125a axis has not been studies in sepsis yet." (PMID 32309886, 2020). "Although most of the lncRNAs regulate none or merely a single sepsis module, FENDRR, MALAT1, TUG1, CRNDE, and ANCR connect multiple sepsis modules with the connectivity of 14, 10, 10, 8, and 5, respectively, which are expected to have high potentials to be involved in the sepsis progress." (PMID 32471511, 2020).